NOTCH3 (notch receptor 3)
Diseases named in the same sentence as NOTCH3 in open-access papers (continued):
Sharing a sentence is not in itself a finding about the gene and the disease.
ovarian carcinoma (continued). "NOTCH3 pathway activation in HGSOC correlates with ovarian cancer progression and contributes to epithelial-mesenchymal transition (EMT) and chemoresistance." (PMID 34758842, 2021). "For example, two different GSIs, MRK-003 and GSI-1, inhibited cell proliferation and induced apoptosis through Notch3 inhibition in Notch3-overexpressing lung and ovarian cancer cell lines, respectively." (PMID 34680255, 2021). "BRD4 binds to the promoter regions of NOTCH3 in ovarian carcinoma, and inhibition of BRD4 activity is associated with lower expression of NOTCH3 mRNA and protein, as well as the expression NOTCH3 target genes." (PMID 34758842, 2021). "Given that both MSI-1 and MSI-2 are negatively correlated with NUMB and positively correlated with NOTCH-3 in our analyses, this seems applicable to ovarian cancer as well." (PMID 34768932, 2021). "Overexpression of Notch3 also enriches ovarian cancer cells with stem-like cell properties, leading to chemoresistance to platinum-based therapy." (PMID 34277625, 2021). "The Kaplan–Meier curve and log rank test analyses revealed that the high expression of Notch3 mRNA had a lower progression-free survival (PFS) rate in all pathological types of ovarian cancer, especially in serous ovarian cancer." (PMID 34277625, 2021). "Further study showed that IL-8 induced cancer cell stemness via the activation of Notch3 and that the high level of IL-8 in ascites was positively correlated with the expression of Notch3 in ovarian cancer tissues." (PMID 34277625, 2021). "In ovarian cancer, the antiproliferative effects of WA were related to abolished Notch1 and Notch3 expression and AKT signaling inhibition." (PMID 34680255, 2021). "NOTCH3 is another oncogene of high relevance in ovarian carcinoma, which has been recently identified as being directly regulated by BRD4 in HGSOC." (PMID 34758842, 2021). "lncRNA TUG1 also regulated aurora kinase A (AURKA), or sponged miR-1299 by up-regulating notch receptor 3(NOTCH3) to promote the proliferation and invasion of epithelial ovarian cancer cells." (PMID 34039257, 2021). "In our study, we found that the transcription factor BRD4 positively regulated the transcription of Notch3 and verified this result in a study of ovarian cancer." (PMID 34834420, 2021). "Among Notch receptors, high expression of Notch3 plays a particularly important role in ovarian cancer resistance to platinum-based compounds." (PMID 34680255, 2021). "In ovarian cancer, Notch3 and Notch1 usually activate multiple signaling pathways to participate in cancer development." (PMID 34277625, 2021). "The plant-derived substance mangiferin interfered with the activation of the Wnt/β-catenin pathway and induced cancer cell apoptosis in a Notch3-dependent manner, sensitizing ovarian carcinoma cells to cisplatin in time- and dose-dependent manners." (PMID 34680255, 2021). "Notch 3 is proposed as a candidate oncogene, the Notch 3 signaling pathway as involved in the tumor progression of ovarian carcinoma, and higher Notch 3 expression as a possible independent, poor prognostic factor." (PMID 33435147, 2021). "Here we demonstrate that in an in vivo mouse model of disseminated ovarian cancer, Notch3 activity decreases survival, upregulates expression of adhesion genes, and increases tumor cell affinity for extracellular matrix in the peritoneal wall." (PMID 32525899, 2020). "Our examination of the role of Notch3 signaling highlights the importance of adhesion in metastasis, and suggests new targets for controlling ovarian cancers." (PMID 32525899, 2020). "We propose a novel model for Notch3 action in ovarian cancer where Notch3 activation leads to increased seeding of detached tumor cells to new sites in the peritoneum." (PMID 32525899, 2020).
ovarian carcinoma (continued). "Phosphorylation of PHB by c-Kit promotes ovarian cancer stem cell survival and proliferation through activation of not only the β-catenin signaling pathway but also the Notch3 signaling pathway." (PMID 32169072, 2020). "Expression of Notch3 and activation of its downstream pathway is strongly correlated with poor prognosis in ovarian cancer." (PMID 32525899, 2020). "Our data in 3 different ovarian cancer cell lines consistently suggest that Notch3 activation leads to increased likelihood of tumor cell binding to new sites in the peritoneum." (PMID 32525899, 2020). "Jagged-1 (Jag1) has been identified as the primary NOTCH3 ligand in ovarian carcinoma and Jag1/NOTCH3 interaction constitutes a juxtacrine loop promoting proliferation and dissemination of EOC cells within the intraperitoneal cavity." (PMID 33316986, 2020). "We generated a CRISPR-mediated and more complete NOTCH3 knockout in the HGSOC PE04 cell line and shown here that NOTCH3-KO has dramatically delayed tumor development in vivo, supporting the importance of NOTCH3 in tumorigenesis in ovarian cancer." (PMID 33316986, 2020). "MiR-136 also inhibits cell survival, proliferation, cancer stem cell spheroid formation, and tumor angiogenesis in paclitaxel-resistant ovarian cancer cells by targeting Notch3." (PMID 32074085, 2020). "The protein coding gene Notch3 is amplified and overexpressed in the majority of high-grade serious ovarian carcinoma (HGSOC)." (PMID 32776013, 2020). "We demonstrate that in the mouse ID8 IP2 and human OVCA429/OVSAHO ovarian cancer cell lines, Notch3 signaling upregulates the collagen I receptor subunit, ITGA1." (PMID 32525899, 2020). "Dll4, Notch 1, Notch 3 or Jagged 1 are overexpressed in ovarian cancer suggesting that Notch signaling is primordial in ovarian cancer." (PMID 32014047, 2020). "Taken together, these data show that Notch3 signal activation in this model of ovarian cancer reduces survival and leads to an increase in ascites accumulation without substantially increasing tumor cell proliferation." (PMID 32525899, 2020). "NOTCH3 overexpression is related to the recurrence of ovarian cancer and confers resistance to carboplatin." (PMID 33316986, 2020). "Notch3 expression levels also correlate with tumorigenic phenotypes, including proliferation, viability, cell cycle arrest, and apoptosis, in ovarian cancer cell lines in vitro indicating a role in tumor growth." (PMID 32525899, 2020). "Mutations removing the Nedd4 family ubiquitin ligase gene WWP2 are commonly found in ovarian cancer and lost WWP2 activity is associated with decreased Notch3 lysosomal degradation and increased signalling activity." (PMID 32210034, 2020). "Our data demonstrate that activating Notch3 signaling is sufficient to accelerate disease progression and increase ascites accumulation in a mouse model of ovarian cancer, ID8 IP2 in the peritoneal cavity." (PMID 32525899, 2020). "DLGAP5 is also a direct downstream target of NOTCH3, which partially explains the mechanism of how NOTCH3 activation promotes ovarian cancer from the perspective of mitotic aberrations." (PMID 32782440, 2020). "Previous literature has suggested that Notch3 expression affects ovarian cancer by increasing survival, particularly anchorage-independent survival in peritoneal fluid." (PMID 32525899, 2020). "It was also reported that notch receptor 3 (NOTCH3) is a transcriptional activator of Pbx1 in ovarian cancer." (PMID 33402862, 2020). "Notch3 inhibition similarly reduced proliferation and induced apoptosis, indicating that Notch3 doesn’t just induce growth, but is a critical cell survival factor in some ovarian cancers." (PMID 32525899, 2020). "Activation of Notch3 dependent pathway in ovarian cancer regulates ovarian cancer cells (OCC) adhesion to peritoneal cells and cancer cell metastatic outgrowth." (PMID 31182109, 2019). "Hes1 locus is amplified in 2–25% in breast and 2–22% in ovarian cancer, followed by Hey1, Notch2 and Notch3." (PMID 31470883, 2019).
ovarian carcinoma (continued). "The authors also showed that Notch3 overexpression in ovarian cancer cells results in the expansion of a subpopulation of cancer stem cells, defined as a side-population of cells, and that it contributes to a significant increase in resistance to cisplatin." (PMID 31261739, 2019). "Together, these data demonstrated that Notch3-specific inhibition resensitizes paclitaxel-resistant ovarian cancer cells to paclitaxel with an efficacy comparable to GSIs." (PMID 30723507, 2019). "The anti-proliferative effect of SIRT6 on ovarian cancer cells is related to Notch 3 signaling pathway, which is involved in tumor progression of ovarian carcinoma." (PMID 31591350, 2019). "Overexpression of Notch3 in ovarian cancer cell lines (IOSE-80pc and MPSC1) enhances expression of stem cell markers (NANOG, OCT4, and SOX2) and increases expression of the ABCB1 transporter protein." (PMID 30042330, 2018). "In ovarian cancer, miR-136 suppresses cancer stem cell properties and magnifies the antitumour effects of paclitaxel against chemoresistance by targeting Notch3." (PMID 30470250, 2018). "A recent study in part clarified the molecular mechanisms responsible for NOTCH3 overexpression in ovarian cancer." (PMID 29389895, 2018). "By analyzing 31 fresh HGS ovarian cancer samples, Notch3 amplification correlated with protein expression." (PMID 30042330, 2018). "Other studies showed that miR-136 overexpression inhibits cancer stem cell activity and enhances the anti-tumor effect of paclitaxel against chemoresistant ovarian cancer cells by targeting NOTCH3." (PMID 29389895, 2018). "In ovarian cancer NOTCH3 is believed to play a key role: this receptor was found to be overexpressed in about 20% of serous ovarian cancers that are associated to a poor prognosis." (PMID 29389895, 2018). "SIRT6 inhibits ovarian cancer cell proliferation via Notch3 downregulation, and correlates with ovarian carcinoma prognosis." (PMID 30064416, 2018). "Notch3 mRNA high expression was significantly correlated with favorite PFS for all ovarian cancer patients." (PMID 28415574, 2017). "Jagged-1/Notch3 interaction constitutes a juxtacrine loop promoting proliferation in ovarian cancer cells." (PMID 28415574, 2017). "Inactivation of Notch3 suppressed cell proliferation and induced apoptosis in the ovarian cancer cells." (PMID 28415574, 2017). "Our data also support a positive regulatory loop between Jagged1 and Notch3 in human myogenic cells, as also reported for ovarian cancer cells." (PMID 29194448, 2017). "Our results showed that Notch3 mRNA high expression was significantly correlated to favorite PFS for all ovarian cancer patients." (PMID 28415574, 2017). "The over expressions of Dll4, Notch 1, Notch 3 or Jagged 1 suggest that Notch signalling plays a key role in angiogenesis in ovarian cancer." (PMID 28284219, 2017). "By TargetScan database and a luciferase reporter assay, we identified miR-150 directly targets Notch3, which is a key oncogene in ovarian cancer." (PMID 29069826, 2017). "Notch3 mRNA high expression was significantly correlated to favorite PFS for all ovarian cancer patients." (PMID 28415574, 2017). "Up-regulation of the Notch3 and increased expression of the Jagged2 was reported in ovarian cancers." (PMID 27626163, 2016). "The correlation analysis of Notch3 expression and pS6 indicated a positive correlation between these two proteins in ovarian epithelial cancer (rs = 0.668, p < 0.01)." (PMID 27445438, 2016). "A recent study on ovarian cancer demonstrated that Notch3 increased resistance to platinum-based chemotherapy and the cancer stem cell population within the tumor." (PMID 28036048, 2016). "The immunohistochemistry results show that Notch3 was mainly expressed in the cytoplasm and/or nucleus of ovarian epithelial cancer cells, while pS6 was mainly expressed in the cytoplasm (data not shown)." (PMID 27445438, 2016).
ovarian carcinoma (continued). "In conclusion, Notch3 and pS6 are significantly related to ovarian epithelial cancer development and prognosis, and their combination represents a potential biomarker and therapeutic target in ovarian tumor angiogenesis." (PMID 27445438, 2016). "Notch3 expression in ovarian epithelial cancer was significantly higher than in normal ovarian tissue (p < 0.01) and ovarian cystadenoma (p < 0.01), and Notch3 expression in ovarian cystadenoma was much higher than in normal ovarian tissue (p < 0.01)." (PMID 27445438, 2016). "A follow-up survey of 64 patients with ovarian epithelial cancer showed that patients with high Notch3 and pS6 expression had a shorter survival time (p < 0.01), in which the clinical stage (p < 0.05) and Notch3 expression (p < 0.01) played important roles." (PMID 27445438, 2016). "The positive expression rates of Notch3 in normal ovarian tissue, ovarian cystadenoma, and ovarian epithelial cancer were 16.7% (5/30), 70.0% (21/30), and 91.7% (110/120), respectively." (PMID 27445438, 2016). "Ectopic expression of WWP2 reduced tumorigenicity of ovarian cancer cells, and counteracted Notch3-mediated phenotypes, including promotion of cancer stem-like cell phenotype and platinum resistance, further supporting its tumor suppressor role." (PMID 25356737, 2014). "Overexpression of NICD3 (the constitutively active form of Notch3) in OVCA429 ovarian cancer cells (OVCA429/NICD3) renders them resistance to carboplatin treatment compared to OVCA429/pCEG cells expressing an empty vector." (PMID 25010594, 2014). "If WWP2 is a negative regulator of Notch3, its expression is expected to be down-regulated in ovarian cancer as compared to normal tissues." (PMID 25356737, 2014). "More recently, HURP has been demonstrated to be the direct target gene of NOTCH3, as growth inhibition in ovarian cancer cells induced by pharmacological or RNA interference-mediated NOTCH inhibition is notably prevented by the enforced expression of HURP." (PMID 25364424, 2014). "One study reported upregulation of the Notch3 gene in all analyzed ovarian cancers, while the second study reported increased Jag2 gene expression in ovarian cancer cell lines compared with benign controls." (PMID 25366565, 2014). "Analysis of The Cancer Genome Atlas dataset showed that the majority of ovarian carcinomas harbored homozygous or heterozygous deletions in WWP2 locus, and there was an inverse correlation in the expression levels between WWP2 and Notch3 in ovarian carcinomas." (PMID 25356737, 2014). "Taken together, MSeA can synergistically sensitize Notch3-activated OVCA ovarian cancer cells to the traditional carboplatin treatment at pharmacologically achievable concentrations." (PMID 25010594, 2014). "Notch3 gene amplification occurs in ovarian carcinoma, and rearrangement occurs in a subset of malignant glomus tumors." (PMID 25356737, 2014). "In this study, using comprehensive proteome microarray, we have identified WWP2, a NEDD4 family member of E3 ubiquitin ligase, as a negative regulator of Notch3 signaling in ovarian cancer." (PMID 25356737, 2014). "Ovarian cancer cells, in which Notch3 was frequently amplified and overexpressed, are dependent on the Notch3 signaling pathway for cellular survival and growth." (PMID 25148538, 2014). "Taken together, our results provide evidence that WWP2 serves as a tumor suppressor by negatively regulating Notch3 signaling in ovarian cancer." (PMID 25356737, 2014). "In particular, Notch3 is overexpressed in 66% of high grade ovarian carcinoma, 22% of which at stages II–IV exhibit altered Notch signaling." (PMID 25010594, 2014). "Abundant evidence suggests that the interaction between Notch3 and Jagged1 plays a key role in the tumorigenesis of numerous diverse malignancies, including ovarian cancer, colorectal cancer and multiple myeloma cells." (PMID 23426998, 2013).
ovarian carcinoma (continued). "Amplification and overexpression of the Notch 3 gene are frequently found in ovarian cancer tissues, and Notch 3 expression correlates with poor prognosis of ovarian cancer patients." (PMID 23528891, 2013). "In this study, Notch 3 overexpression increased the ovarian cancer side population, while treatment with a Notch 3 inhibitor depleted the ovarian CSC/TIC population and increased sensitivity to platinum." (PMID 23528891, 2013). "Although the role of hypoxia in DLG7 expression has not been demonstrated directly, it has been inferred by the finding that DLG7 is a Notch 3 target in ovarian cancer cells." (PMID 24349376, 2013). "On the basis of the involvement of Notch signaling in the chemoresistance of ovarian cancer, a recent study demonstrated that the Notch signaling pathway, specifically Notch 3, is critical for platinum resistance in ovarian CSC/TICs." (PMID 23528891, 2013). "Notch3 has been shown to be important in several solid tumours, with gene amplification (19p13.12) detected in breast and ovarian carcinoma." (PMID 23226563, 2012). "Knockdown of either Notch3 or RBPjk, a Notchinteracting transcription factor critical in Notch signaling, suppressed Jagged1 expression in ovarian cancer cells." (PMID 20953350, 2010). "Among different Notch3 ligands, Jagged1 is most dominant in ovarian cancer, and Notch3 pathway activity correlated with Jagged1 expression level in ovarian carcinoma tissues." (PMID 20953350, 2010). "Different ovarian cancer cell lines were tested, and OVCAR3 and OVMANA ovarian cancer cell lines were used because both cell lines expressed abundant endogenous Notch3 and Jagged1." (PMID 20953350, 2010). "Taken together, our data suggested a positive regulatory loop between Notch3 and its ligand, Jagged1, in ovarian cancer cells." (PMID 20953350, 2010). "Moreover, Au-Fe3O4 heterogeneous nanoparticles were developed to deliver VEGF aptamer-Notch3 siRNA chimera specifically to VEGF-positive ovarian cancer cells to silence the target Notch3 gene and enhance the antitumor effects." (PMID 40860190, 2025). "Likewise, a positive feedback loop between Notch3 and Jagged1 has been described in ovarian cancer, where their co-expression forms a functional signaling network." (PMID 41294868, 2025). "Together these results suggest the effect of HA on DAB2 expression in ovarian cancer may be dependent on Notch3." (PMID 37815603, 2023). "In ovarian cancer, Notch3 correlates with reduced OS, PFS, metastasis and therapy resistance." (PMID 37815603, 2023). "Moreover, NR2F6 overexpression has previously been described to promote the chemoresistance of epithelial ovarian cancer via activation of Notch3." (PMID 37370765, 2023). "Notch 3 activation was found to increase the expression of ITGA1 in ovarian cancer cells." (PMID 35053843, 2022). "Targeting NOTCH3 inhibits the growth of ovarian cancer and induces apoptosis." (PMID 35073251, 2022). "Notch3 is a known critical regulator of cancer stem cells (CSC) in ovarian carcinoma." (PMID 35884426, 2022). "The results showed that the cleaved Notch3 was decreased in IL-8 knockdown cells but was increased in IL-8 overexpression cells, indicating that IL-8 may promote ovarian cancer cell stemness through the activation of Notch3 signaling." (PMID 34277625, 2021). "In 3-D culture, IL-8 induced the spheroid formation of ovarian cancer cells, whereas the IL-8-mediated cell stemness might be mediated through the Notch3 signaling." (PMID 34277625, 2021). "In addition, they revealed that SIRT6 suppressed the expression of Notch 3 through downregulation of its expression both at the mRNA and protein levels in ovarian cancer cells." (PMID 33435147, 2021).